STEAP1 (STEAP family member 1)
Diseases named in the same sentence as STEAP1 in open-access papers (continued):
Sharing a sentence is not in itself a finding about the gene and the disease.
prostate carcinoma (continued). "NOD scid gamma (NSG) mice were engrafted s.c. with the human STEAP1-positive prostate cancer cell line 22Rv1 and, once the tumors were palpable, treated with STEAP1 CAR T cells, CD19 CAR T cells, or NT T cells." (PMID 35860008, 2022). "Consistent with a previous study, STEAP1 was downregulated in prostate cancer tissues compared with normal samples and negatively associated with promoter methylation levels integrating both vitro and silico analysis." (PMID 35313641, 2022). "STEAP1 expression is significantly increased in prostate cancer, and silencing STEAP1 expression can inhibit the proliferation of prostate cancer cells and promote cell apoptosis." (PMID 35346237, 2022). "Since STEAP1–4 are highly expressed and localized to PCa tumors, they are a promising avenue for targeted therapy in prostate cancer." (PMID 36011027, 2022). "Currently, investigations of STEAP1 mainly focus on prostate cancers and show that expression of STEAP1 is elevated compared with normal prostate tissue." (PMID 34778263, 2021). "STEAP1 is known to be enriched on the cells of the prostate with potential clinical significance in prostate cancer." (PMID 33589770, 2021). "Recently, it was shown in prostate cancer that patients’ plasma samples presented significantly higher STEAP1-positive EVs compared to healthy individuals, as analyzed by nanoscale flow cytometry." (PMID 34604225, 2021). "An evaluation of STEAP1 in prostate cancer tissue was also performed using established prostate cancer cohort data (TCGA, MSKCC, and SU2C/PCF Dream Team)." (PMID 33589770, 2021). "Then, we analyzed the expression of STEAP1 in the TCGA database, and the results showed that STEAP1 was overexpressed in human prostate cancer compared to adjacent normal prostate tissues." (PMID 34358202, 2021). "STEAP1-positive EVs were quantified for 121 males with prostate cancer and 55 healthy age-matched control males." (PMID 33589770, 2021). "Knockdown of STEAP1 gene has been correlated with inhibited cell viability and proliferation and enhanced apoptosis in LNCaP prostate cancer line." (PMID 33557050, 2021). "Evaluation of STEAP1-positive EVs by nanoscale flow cytometry identified a significant increase in prostate cancer patient plasma compared to healthy males." (PMID 33589770, 2021). "It is commonly found that STEAP1 is up-regulated in a variety of tumor tissues, especially in prostate cancer." (PMID 34778263, 2021). "STEAP1 is a tumor suppressor gene in colon, breast and gastric cancers, but acts as an oncogene in prostate cancer." (PMID 33535185, 2021). "Compared with tumor-adjacent normal tissues and benign prostatic hyperplasia (BPH) tissue, STEAP1 was upregulated in prostate cancer and prostatic intraepithelial neoplasia (PIN)." (PMID 32265985, 2020). "The mRNA level of STEAP1 was low in different types of malignant tumors except for prostate cancer, and the protein level of STEAP1 was medium expressed in the tissues of lung cancers, low or not detected in other types of cancers." (PMID 32802887, 2020). "Previous evidence reveals that STEAP1 is aberrantly high expressed in prostate cancer and predicted as a prostate-specific cell-surface antigen." (PMID 32802887, 2020). "It was proved that the expression of STEAP1 in prostate cancer is significantly increased, and silencing STEAP1 expression can inhibit the proliferation of prostate cancer cells and promote apoptosis." (PMID 32802887, 2020). "STEAP1 is overexpressed in many kinds of cancers, such as prostate cancer, colon cancer, bladder cancer, ovarian cancer, pancreatic cancer, testicular cancer, breast cancer, cervical cancer and Ewing sarcoma." (PMID 33128353, 2020).
prostate carcinoma (continued). "In fact, it has been shown that monoclonal antibodies designed against STEAP1 can inhibit bladder and prostate cancer in mice models." (PMID 30246786, 2018). "Recently, we have provided evidence that PD-1 blockade in combination with a ChAdOx1-MVA immunisation regime against STEAP1 antigen is successful in improving survival and reducing tumour burden in a transplantable mouse model of prostate cancer." (PMID 28537896, 2017). "For example, prostate cancer patients with STEAP1 overexpression in the tumor portion show significantly poor survival." (PMID 27104516, 2016). "CV9103 is a prostate-cancer vaccine containing self-adjuvanted mRNA (RNActive®) encoding the antigens PSA, PSCA, PSMA, and STEAP1." (PMID 26082837, 2015). "In addition, for prostate cancers, ADCs are primarily focused on six-transmembrane epithelial antigen of prostate 1 (STEAP1), TROP2, prostate-specific membrane antigen (PSMA), CD46, and B7-H3 as the potential targets." (PMID 38933670, 2024). "Additionally, proteins such as PD-L1, STEAP1, and STEAP2 are associated with aggressive forms of prostate cancer." (PMID 39766159, 2024). "Furthermore, a recent study demonstrated the development of a chimeric antigen receptor (CAR) against STEAP1, which showed remarkable efficacy against prostate cancer cells both in vitro and in vivo." (PMID 37909017, 2023). "STEAP1 has been recently investigated in a variety of tumor tissues in addition to prostate cancer." (PMID 37909017, 2023). "In terms of diagnosis, immunohistochemical analysis of prostate cancer specimens with a range of Gleason scores revealed that STEAP1 could be a suitable candidate to distinguish patients with cancer from patients without tumor." (PMID 37909017, 2023). "Knockdown of STEAP1 induces apoptosis and inhibits proliferation in prostate cancer cells." (PMID 37909017, 2023). "Therefore, STEAP1 extracellular vesicles can be used for screening to improve the clinical management of prostate cancer." (PMID 37909017, 2023). "Another finding in prostate cancer revealed that knockdown of STEAP1 could inhibit cell growth and induce apoptosis in prostate cancer cells." (PMID 35313641, 2022). "Furthermore, targeting STEAP1 through a specific single chain antibody blocked gap junctions and resulted in a reduction of 80–90% of the intercellular communications between prostate cancer cells." (PMID 33557050, 2021). "As for prostate cancer, researchers are focusing on STEAP1, TROP2, PSMA, CD46 and B7-H3 as optimal antigens which may be targeted by ADCs." (PMID 33557050, 2021). "STEAP1 was identified on EVs in prostate cancer patient plasma." (PMID 33589770, 2021). "In this work, we successfully extracted and purified the native full-length human STEAP1 protein from LNCaP prostate cancer cells by exploring two traditional hydrophobic matrices—Butyl- and Octyl-Sepharose—enhancing their chromatographic behavior and performance." (PMID 34576175, 2021). "A DNA vaccine strategy based on STEAP1 was evaluated as a possible treatment for prostate cancer." (PMID 34358202, 2021). "Targeting STEAP1 expression may potentially inhibit the proliferation of and induced apoptosis in prostate cancer cells." (PMID 32265985, 2020). "STEAP1 has also been identified as a prognostic marker in Ewing’s sarcoma and prostate carcinoma." (PMID 27104516, 2016). "STEAP1 gene is overexpressed in several kinds of tumors, particularly in prostate cancer." (PMID 25053991, 2014). "Interestingly, STEAP1 is highly expressed in prostate cancer." (PMID 36829936, 2023). "The potential implication of these data is that treatment with STEAP1-BBζ CAR T cell therapy and resultant loss of STEAP1 tumor antigen expression in prostate cancer may result in further immunotherapy resistance through impaired antigen processing and presentation." (PMID 37041154, 2023).
prostate carcinoma (continued). "We next hypothesized that broadening the antitumor immune response with CBD-IL-12 therapy could improve the therapeutic efficacy of STEAP1-mBBζ CAR T cell therapy in prostate cancer by combating tumor antigen heterogeneity and rescue of antigen processing and presentation." (PMID 37041154, 2023). "Although most of the research related to STEAP1 was conducted in prostate cancer, we believe that STEAP1 could also be an ideal target in other types of malignant tumors as growing evidence has revealed the overexpression of STEAP1 in cancerous cells compared to the normal counterpart." (PMID 37909017, 2023). "The six-transmembrane epithelial antigen of the prostate 1 (STEAP1) is exceptionally overexpressed in PCa, maintaining high expression even in the castration-resistant prostate cancer (CRPC) stage, making it a promising target for diagnosis and treatment." (PMID 40299363, 2025). "In contrast to the expression of well-established prostate cancer targets (PSMA, PSCA, and STEAP1), KLK2 expression is highly prostate-specific." (PMID 40627156, 2025). "There is limited information on the relevance of STEAP1 and STEAP2 to the progression and survival of prostate cancer." (PMID 40214422, 2025). "We have developed a chimeric antigen receptor (CAR) against the six-transmembrane epithelial antigen of prostate-1 (STEAP1), which is expressed in prostate cancer, Ewing sarcoma, and other malignancies." (PMID 38203757, 2024). "The keywords and combinations used were: "antibody-drug conjugates" or "ADC" and "prostate cancer" and "PSMA" or "TROP2" or "STEAP1" or "TF" or "HER2" or "SLC44A4" or "B7-H3" or "CD46" or "TM4FS1" or "DLL-3," with no range date filter." (PMID 36874351, 2023). "Modified anti-STEAP1 antibody-PROTAC conjugates with a BRD4 ligand and a VHL ligand, particularly STEAP1-9d (DAR 5.9), afforded the highest degradation of the BRD4 protein with a DC50 value of 0.025 nM using PC3-S1 prostate cancer cells." (PMID 37489365, 2023). "Six-transmembrane epithelial antigen of prostate (STEAP) 1–4 consist of a family of five metalloproteinases, namely STEAP1, 1B, 2, 3 and 4, which (with the exception of STEAP3) are commonly expressed in prostate cancer." (PMID 36831514, 2023). "The six-transmembrane epithelial antigen of prostate 1 (STEAP1), first identified in advanced prostate cancer, is a cell surface protein that functions as a transporter." (PMID 37909017, 2023). "Here the authors describe the design of STEAP1 directed CART cells and show their antitumor activity in preclinical models of prostate cancer, also in combination with a collagen binding domain-IL-12 fusion cytokine." (PMID 37041154, 2023). "And STEAP1 and STEAP2 have previously been reported as potential markers, especially for aggressive prostate cancer." (PMID 35346237, 2022). "Of note, imaging through anti-STEAP1 antibody 89Zr-DFO-MSTP2109A revealed high SUV in bone and soft tissue localization from prostate cancer." (PMID 33557050, 2021). "In four different patient-derived prostate cancer models, with varying TENB2 and STEAP1 expression, immunoPET predicts MMAE-conjugated ADC treatment efficacy." (PMID 27029064, 2016). "For prostate cancer, TENB2 and STEAP1 have been recently identified as targets of interest for ADC development." (PMID 27029064, 2016). "Prostate cancer is rich in tumor associated antigens such as, but not limited to, PSMA, PSCA, hK2, and STEAP1 and there is strong biologic rationale for employment of T-cell redirecting BiTEs within the prostate cancer disease space." (PMID 38801069, 2024). "Prostate cancer expresses a high number of TAAs, such as prostate-specific membrane antigen (PSMA), prostatic acid phosphatase (PAP), prostate-specific antigen (PSA) or six-transmembrane epithelial antigen of the prostate-1 (STEAP1)." (PMID 38473341, 2024).
prostate carcinoma (continued). "Anti-STEAP1 antibody-PROTAC conjugates with a BRD4 ligand and a VHL ligand, particularly STEAP1-5a (drug-to-antibody ratio (DAR) 6.0), afforded degradation of the BRD4 protein with a DC50 value of 0.67 nM using PC3-S1 prostate cancer cells." (PMID 37489365, 2023). "Notably, previous studies have shown that CD81, METTL3, STEAP1, and TRIM28 contributed to the progression of prostate cancer." (PMID 37958805, 2023). "STEAP1 is particularly over-expressed in prostate cancer (PCa), in contrast with non-tumoral tissues and vital organs, unveiling its specificity for cancer microenvironments." (PMID 34576175, 2021). "Clarifying the regulation of STEAP1 as well as the expression and function of STEAP1B on cells may open novel strategies for diagnosis and treatment of prostate cancer." (PMID 25053991, 2014). "However, despite these promising findings, the antiproliferative effect of NGP-43 on prostate cancer PC3 cells with elevated levels of STEAP-1 in vitro was not evident." (PMID 38773495, 2024). "The SwR-CAR T cell activity was assessed against a panel of STEAP1+/− prostate cancer cell lines with or without over-expression of TGFβ, or with added TGFβ, by use of flow cytometry cytokine and killing assays, Luminex cytokine profiling, cell counts, and flow cytometry phenotyping." (PMID 36830995, 2023). "Importantly, our STEAP1-BBζ CAR is capable of inducing T cell activation and target cell cytolysis even in low antigen density conditions, as evidenced by reactivity against the PC3 prostate cancer model." (PMID 37041154, 2023). "STEAP1 (six-transmembrane epithelial antigen of the prostate 1), a transmembrane channel used as ions/proteins transporter, represents an ideal target for ADC-based therapies because of its high expression in prostate cancer cells whereas it is very low expressed in normal tissues." (PMID 33557050, 2021). "Samples were stained and analysed for intensity of the Seven Transmembrane Epithelial Antigen of the Prostate (STEAP)-1, -2, -3, -4 and the Divalent Metal Transporter 1 (DMT1) proteins to determine suitable biomarkers for classification of patients likely to develop aggressive prostate cancer." (PMID 31393902, 2019). "With regard to metastatic castration-resistant prostate cancer, though there are no ADCs approved for prostate cancer, there are some ADCs targeting different antigens in clinical studies, such as PSMA, TROP-2, STEAP1, TF and DLL-3." (PMID 40959458, 2025). "Although STEAP1 CAR-T has not yet been applied in the clinical trial setting, it showed promising anti-tumor activity in prostate cancer with CAR-T cell expansion and infiltration into the tumor microenvironment both in vivo and in vitro." (PMID 37909017, 2023).
Ewing sarcoma (24 papers, 2014 to 2025). A small round cell tumor that lacks morphologic, immunohistochemical, and electron microscopic evidence of neuroectodermal differentiation. "STEAP1 is a tumor-associated antigen, which is overexpressed in many cancers, including Ewing sarcoma (EwS)." (PMID 32610710, 2020). "High STEAP1 mRNA expression in some Ewing family tumors can be associated with cancer metastasis and short survival; however, other Ewing’s sarcoma patients with high STEAP1 protein expression show associated good clinical outcomes." (PMID 27104516, 2016). "High STEAP1 expression in Ewing sarcoma has been reported to be associated with an improved outcome." (PMID 24950699, 2014). "STEAP1 is widely overexpressed in various cancers, such as bladder cancer and Ewing’s sarcoma, but is exceptionally high in PCa." (PMID 40299363, 2025). "More recent studies have unveiled that NKX2-2, in conjunction with EWSR1-FLI1, binds to the promoter region of STEAP1 (six transmembrane epithelial antigen of the prostate 1), a gene crucial for the survival of Ewing sarcoma." (PMID 37894854, 2023). "Previous studies have found that STEAP1 and STEAP2 are associated with poorer patient outcomes through comprehensive microarray screening of bone marrow aspirates in Ewing’s sarcoma patients." (PMID 35346237, 2022). "In human Ewing sarcoma cell lines, STEAP1 knockdown decreases proliferation, invasion, growth, and metastatic potential, suggesting a crucial role for STEAP1 in tumorigenic properties in patient-derived Ewing sarcoma cell lines." (PMID 36430490, 2022). "STEAP1, STEAP2, and STEAP4 have been evaluated as possible diagnostic and prognostic biomarkers in glioblastoma, breast cancer, Ewing sarcoma, lung cancer, and PCa." (PMID 36011027, 2022). "Other anti-STEAP1 therapeutics are under investigation for renal cell carcinoma, urothelial carcinoma, and Ewing sarcoma." (PMID 36011027, 2022). "Our findings corroborate recently reported finding that STEAP1 potentiates oxidative properties and invasiveness in Ewing tumor cells." (PMID 30246786, 2018). "STEAP-1 is a cell membrane protein that acts as an ion channel or transporter protein and is highly expressed in prostate, breast, pancreas, bladder, gastrointestinal tract, testicular, ovarian, and cervical cancers, Ewing sarcoma, and melanoma." (PMID 37631232, 2023). "Interestingly, STEAP1 expression is known to be upregulated in Ewing sarcoma, prostate cancer, and breast cancer." (PMID 36430490, 2022). "Furthermore, STEAP1 silencing inhibited proliferation, clonal formation, and invasion in vitro and in vivo in Ewing’s tumor." (PMID 32265985, 2020). "Furthermore, STEAP1 is reportedly upregulated in Ewing’s tumor and colorectal cancer, and the prognosis of patients with high STEAP1 expression levels was better than that of patients with low expression levels." (PMID 32265985, 2020). "Analysis of the transcriptomes and proteomes of Ewing’s tumors, together with functional studies, has also revealed a correlation between STEAP1 expression and oxidative stress responses, including elevation of levels of reactive oxygen species that promote expression of proinvasive genes." (PMID 27104516, 2016). "In contrast, STEAP1 expression has also been reported to promote invasiveness in Ewing tumors." (PMID 24950699, 2014). "A more recent surfaceome analyses revealed many new Ewing sarcoma cell surface targets including ENPP1 and CDH11 in addition to known IL1RAP, STEAP1, ADGRG2 and CD99, providing newer cell surface targets for immunotherapeutic application in Ewing sarcoma." (PMID 40442778, 2025). "Furthermore, a key oncogenic driver in pediatric Ewing’s sarcoma is a chromosomal translocation giving the fused EWSFLI1 gene, which leads to the upregulation of STEAP1." (PMID 38203757, 2024).